INS (insulin)
Diseases named in the same sentence as INS in open-access papers (continued):
Sharing a sentence is not in itself a finding about the gene and the disease.
type 1 diabetes (continued). "Consistent with being a Kv1.3 inhibitor, SD effectively reduces islet β cell damage in a rodent model of STZ-induced type I diabetes and increases levels of plasma insulin, thereby lowering blood glucose, suggesting that SD has a therapeutic effect on autoimmune diseases." (PMID 25937895, 2014). "Type 1 diabetes (T1D) results from destruction of the insulin-producing beta cells of the pancreas." (PMID 25405480, 2014). "The decline in insulin production in patients diagnosed with type 1 diabetes is variable." (PMID 24121625, 2014). "The mean age for type 1 diabetes (combining insulin-dependent and specifically type 1) is younger than the mean age at onset for the other diseases, reflecting the fact that some of these cases occur among juveniles, although in recent years the majority of type 1 diabetes now occurs among adults." (PMID 23735465, 2013). "The women with type 1 diabetes received dietary counseling and intensive insulin therapy." (PMID 24319455, 2013). "Type 1 diabetes mellitus (T1DM) is characterized by autoimmune destruction of insulin-producing beta cells of pancreatic islets by CD4+ cytotoxic T lymphocytes with the contribution of CD8+ helper T lymphocytes, which leads to permanent impairment of glucose metabolism." (PMID 23936838, 2013). "Thus, such as endogenous insulin, the effective insulin treatments influence the lipid transfers in well-controlled patients with type 1 diabetes." (PMID 24499591, 2013). "The use of a bioartificial endocrine pancreas could be the definitive solution to type 1 diabetes, be it by development of “insulin pumps” which respond automatically to blood glucose levels or be it by development of tissue-engineered pancreas." (PMID 24009755, 2013). "Apart from being clinically well tolerated, the addition of ORMD-0801 oral insulin capsules to subcutaneous insulin injection regimens among type I diabetes patients resulted in a synergistic reduction in blood glucose concentrations which was most prominent during the early evening hours." (PMID 23593142, 2013). "Summarized, copeptin increases in patients with type 1 diabetes upon insulin induced hypoglycaemia." (PMID 24023652, 2013). "However, the results suggested that those with type I diabetes mellitus required more insulin, due to the fact that the slope of the regression line was steeper." (PMID 23533796, 2013). "Type 1 diabetes results from the autoimmune destruction of insulin-producing beta cells." (PMID 24223733, 2013). "Additionally, the study found that NSNHEs are not only problematic for those using insulin or only those with Type 1 diabetes." (PMID 22825805, 2013). "Before the discovery of insulin, diabetes mellitus type I (DM1) sufferers died very rapidly." (PMID 24396605, 2013). "Indeed, HbA1C-aware patients were more likely than HbA1C unaware patients to report type 1 diabetes, present with a longer disease duration and insulin use, and were more likely to be younger, more educated and report higher income." (PMID 23800376, 2013). "In the group of previously gestational women (B1), 2 (5.3%) patients had GAD65-Ab-positive values, 1 of whom had low level positivity (<2 IU/mL), and the second, who had a GAD65-Ab value of 16 IU/mL, was diagnosed as type 1 diabetic and is on insulin treatment." (PMID 22654905, 2012). "Achieving artificial tissue homeostasis would be therapeutically relevant for diseases such as Type I diabetes, for instance by transplanting genetically engineered stem cells that stably maintain populations of insulin-producing beta-cells despite normal cell death and autoimmune attacks." (PMID 22829755, 2012). "In a small pilot study of 18 patients (11 males and seven females), pediatric patients who had newly diagnosed type 1 diabetes and who were treated with etanercept had lower A1C and increased endogenous insulin production, suggesting preservation of beta-cell function." (PMID 22234148, 2012).
type 1 diabetes (continued). "An analogous example of a similar disease process affecting children and adolescents in particular is provided by type 1 diabetes, in which insulin-producing beta-cells are destroyed by immunological mechanisms in genetically predisposed individuals with HLA DQB1*0302 and 02 alleles." (PMID 22470453, 2012). "The study is a Danish two-year investigator-initiated, prospective, randomised, open, blinded endpoint (PROBE), multicentre, cross-over trial investigating the effect of insulin analogues versus human insulin on the frequency of severe hypoglycaemia in subjects with type 1 diabetes." (PMID 22727048, 2012). "Another important aspect of low HDL-cholesterol is its relationship to higher insulin daily doses in type 1 diabetes therapy, which may indicate a higher insulin resistance background." (PMID 23270560, 2012). "In type 1 diabetes (T1D) the patients exhibit defective insulin production." (PMID 23024779, 2012). "Patients with type 1 diabetes are always treated with insulin." (PMID 22613296, 2012). "Moreover, intracerebral administration of streptozotocin, a drug known to induce type 1 diabetes by impairing pancreatic β cells when added intravenously, also led to insulin depletion in the brain with subsequent neurodegeneration." (PMID 22369239, 2012). "Most programmes for type 1 diabetes patients also offer education and instruction in the use of flexible intensive insulin therapy, comprising long-acting basal or background insulin injected once or twice daily, and quick-acting bolus insulin adjusted to carbohydrate intake at meals." (PMID 22891794, 2012). "The blood glucose excursions in type 1 diabetes are a function of the input of glucose from food, mainly carbohydrates in the form of easily dissolved starch and sugars, and insulin from subcutaneous insulin stores." (PMID 22650646, 2012). "Our results suggest that insulin may play a significant role in the regulation of microvascular perfusion in patients with Type 1 diabetes through its vasodilation effect and can counteract the effect of acute glucose fluctuations." (PMID 22262970, 2012). "Insulin substitution is the only treatment available for type 1 diabetes at the moment." (PMID 22460761, 2012). "Confusion often arises from the sheer number of preparations, the administration devices currently available and whether the patient has type 1 diabetes (when insulin should neverbe withheld)." (PMID 22613296, 2012). "The chronic autoimmune reaction in type 1 diabetes is directed towards specific beta cell antigens, which include the beta cell surface proteins insulin, PTPRN (which is also known as insulinoma antigen 2 or IA-2) and zinc transporter 8 (also referred to as ZNT8 or SLC30A8)." (PMID 22460761, 2012). "We show that thickening of carotid intima-media, an established surrogate marker of early atherosclerosis, is inversely associated with insulin sensitivity in non-obese adolescent type 1 diabetes." (PMID 23185996, 2012). "In contrast to this, other recent work has demonstrated that administration of oral insulin may help protect residual β-cell function in children and adults with recent-onset type 1 diabetes." (PMID 22500167, 2012). "However, many patients with type 1 diabetes still retain some residual pancreatic β-cell function, and insulin is secreted at subphysiological levels alongside c-peptide." (PMID 22500167, 2012). "In order to determine whether the insulin present in the milk of mothers with type 1 diabetes is synthesised in the mammary gland or is transported from blood, total and endogenous insulin levels were measured in all milk samples in this group (n = 53)." (PMID 22500167, 2012). "The conventional pharmacological treatment of Type 1 diabetes (T1DM) is insulin." (PMID 22240113, 2012). "The insulin-induced intima hyperplasia was also found in type 1 diabetes after balloon injury in rats and may be responsible for accelerated coronary restenosis in human beings." (PMID 21977022, 2012).
type 1 diabetes (continued). "Type 1 diabetes results from the body's failure to produce insulin due to autoimmune or idiopathic destruction of cells, and may require the injection of insulin to control symptoms." (PMID 22611498, 2012). "In adolescents with type 1 diabetes it has been used to promote insulin sensitivity." (PMID 22778966, 2012). "Fallaciously, the occurrence of type I diabetes mellitus where insulin synthesis is known to be completely impaired might be beneficial in breast cancer due to maspin synthesis." (PMID 23675265, 2012). "One pilot randomized cross-over trial showed that sera from subjects with type 1 diabetes treated with glargine stimulated the growth of human breast carcinoma cells to a greater extent than sera from the same patients during treatment with NPH human insulin." (PMID 23209929, 2012). "This study explored the support needs of patients with type 1 diabetes after attending a structured education programme promoting an empowerment approach and training in use of flexible intensive insulin therapy, a regimen now widely advocated and used to manage this condition." (PMID 22891794, 2012). "In type 1 diabetes, the pancreas cannot synthesize enough insulin to maintain euglycemia." (PMID 22611498, 2012). "In this regard, a recent article has shown the insulin concentration required for 50% suppression of hepatic glucose production in a hyperinsulinemic/euglycemic clamp to be almost two times higher in type 1 diabetes than in controls adjusted for age, gender, and HbA1c." (PMID 23270560, 2012). "Postmeal administration of insulin glulisine has been studied in patients with type 1 diabetes, and was shown to provide glycaemic control equivalent to that of premeal insulin glulisine and RHI, with a small but statistically significant body weight loss over 12 weeks." (PMID 21812890, 2011). "Closed-loop insulin delivery presents a tangible treatment option and may serve as a bridge to a cure for type 1 diabetes until stem-cell therapy or similar long-term biologic interventions become available." (PMID 22071283, 2011). "However, most commonly MODY3 acts like a very mild version of type 1 diabetes, with continued partial insulin production and normal insulin sensitivity." (PMID 21504591, 2011). "At present, there are more patients with type 2 than type 1 diabetes receiving insulin treatment." (PMID 21410860, 2011). "Insulin is a major therapeutic agent for patients with type I diabetes." (PMID 21479175, 2011). "Daniela Elleri, MD, is a clinical research fellow in Paediatrics at the Institute of Metabolic Science and Department of Paediatrics, University of Cambridge, UK, who is actively involved in the clinical research studies evaluating closed-loop insulin-delivery systems in people with type 1 diabetes." (PMID 22071283, 2011). "Finally, adult patients with both GHD and type-I diabetes were shown to require less insulin to normalize glucose and therefore suffered from more frequent hypoglycemic events, and these features were normalized after GH therapy." (PMID 21283519, 2011). "Although the mechanism is unclear, the correlation could be related to the degree of glycemic control in type 1 diabetes as optimal glucose control improves insulin sensitivity but may lead to weight gain." (PMID 22164267, 2011). "Despite some limitations concerning comparability mainly resulting from methodological and country specific aspects, insulin glargine (GLA) seems to offer good value for money compared to conventional human insulin (NPH) in patients with type 1 diabetes treated with a basal bolus regimen." (PMID 21978524, 2011). "At present, there is little information about the role of DNCD3 peripheral cells in autoimmunity, particularly in type-1 diabetes (T1D), a disease characterized by the reduction of insulin production subsequent to destruction of pancreatic β-cells by a polyclonal population of self-reactive T-cells." (PMID 20625402, 2010).
type 1 diabetes (continued). "Insulin is essential in type 1 diabetes, including the emergency treatment of ketoacidosis." (PMID 21274337, 2010). "C-peptide replacement together with insulin administration may be beneficial in type 1 diabetes patients." (PMID 20535267, 2010). "In the DCCT, patients with type 1 diabetes randomised to intensive therapy (≥ 3 insulin injections per day or pump therapy) had tighter glycaemic control than those who received conventional treatment (1–2 insulin injections per day) (mean HbA1c: 7.1% vs. 9.1%, respectively)." (PMID 20456170, 2010). "The methodology used may have missed a few type 1 diabetes patients who have been taking treatment, and buying insulin from outside the district." (PMID 20214794, 2010). "This study was designed primarily to evaluate the impact of six months exercise program on glycemic control, plasma lipids values, blood pressure, frequency of hypoglycemia, anthropometric measurements and insulin requirements in a sample of adolescents with type 1 diabetes mellitus." (PMID 20618996, 2010). "Interestingly, the peptide 18 (B11-23) corresponds to the insulin peptide B9-23, which had been identified as an immunodominant epitope of autoimmune T-cell reactivity in type 1 diabetes." (PMID 21059249, 2010). "In a recent press release company developing ORMD-0801 announced successful completion of a an exploratory clinical trial testing the effectiveness of its oral insulin capsule in Type 1 diabetes patients suffering from uncontrolled diabetes, however complete results are not yet out." (PMID 21059246, 2010). "Interestingly, insulin represents a dominant antigen during the development of the immunological processes leading to pancreatic β-cell destruction and (insulin-dependent) type 1 diabetes." (PMID 21059249, 2010). "Although type-1 diabetes can be controlled by insulin injections, individuals who develop the disease may suffer long-term complications that include blindness, kidney failure and premature vascular disease leading to early death." (PMID 20877570, 2010). "Type 1 diabetic (T1DM) patients treated with unmodified regular human insulin (RHI) rarely achieve their glycaemic target and often suffer from postprandial hyperglycaemic excursions, together with an increased risk of hypoglycaemia in the post-absorptive period." (PMID 19709151, 2009). "David (a 12 year old with type 1 diabetes) can now administer his own insulin but his parents always check the dose first as "it could be a matter of life or death with the wrong dose"." (PMID 19117528, 2009). "In type 1 diabetes this can only be achieved with insulin therapy." (PMID 19220880, 2009). "Patients with type 1 diabetes need to inject insulin to survive." (PMID 19997624, 2009). "In addition, during development of type 1 diabetes, insulin synthesis increases in an attempt to reduce high blood glucose levels created by a diminishing beta cell mass." (PMID 19888425, 2009). "Thus, any mechanism resulting in reduced insulin secretion and/or inhibition of the immune response would be likely to result in type 1 diabetes." (PMID 20142874, 2009). "Also, at similar glycaemic levels, the lower insulin-dose after metformin therapy, suggests a glucose-lowering and/or insulin-sensitizing effect of metformin therapy in patients with type-1 diabetes." (PMID 18852875, 2008). "By contrast, replacement of a patient's islets of Langerhans either by whole pancreas transplantation or by isolated islet transplantation is the only treatment of type 1 diabetes that achieves an insulin-independent, constant normoglycaemic state and avoids hypoglycaemic episodes." (PMID 18298656, 2008). "While underlying autoimmunity in type 1 diabetes leads to therapeutic failure after islet or whole pancreas transplantation, insulin-secreting hepatocytes are not targets for recurrent autoimmune destruction." (PMID 18320053, 2008).
type 1 diabetes (continued). "This 24-month, multi-national, open-label, parallel group trial investigated the long-term efficacy and safety of insulin detemir and Neutral Protamine Hagedorn insulin in combination with mealtime insulin aspart in patients with Type 1 diabetes using a treat-to-target concept." (PMID 18387078, 2008). "The aim of this research was to consult stakeholder groups and explore their perspectives on the desirable, important, and feasible characteristics of an Internet-based virtual clinic system for people who have type 1 diabetes and use insulin pumps, and to flag any potential worries or concerns." (PMID 17942385, 2007). "Besides insulin injections, the only other option for treatment of type 1 diabetes is islet transplantation." (PMID 17941991, 2007). "Stimulation of insulin secretion from surrogate beta cells via the production of NO could provide a potential therapy for the treatment of type 1 diabetes." (PMID 17941991, 2007). "We are pursuing the hypothesis that insulin is a primary autoantigenfor type 1 diabetes, and thus thepathogenesis of the disease relates to specific recognition of one or more peptides." (PMID 16295523, 2005). "In accordance with these criteria our diabetic Indian child had the characteristics of type 1 (age less than 5 years at diagnosis, low body weight, positive for IA2 antibodies, genetic markers for type 1 diabetes and in need of insulin treatment since diagnosis)." (PMID 15947838, 2005). "Although autoantibodies in NOD mice are a less prominent feature than in humans with type 1 diabetes, the mice develop autoantibodies to insulin before disease onset, with the suggestion that early production of autoantibodies may predict earlier onset of diabetes." (PMID 41206392, 2026). "Long-acting insulin analogues are the standard of care for Type 1 diabetes (T1D) in high-income countries but remain inaccessible in many low-resource settings." (PMID 41481625, 2026). "Hence, in this study, our primary objective was to assess the effect of video consultations over 1 year, compared with usual care, on the time in range (TiR; the percentage of time spent at glucose levels of 3.9–10.0 mmol/l) in patients with type 1 diabetes managed with insulin pumps." (PMID 41198916, 2026). "Additionally, application of a type 1 diabetes genetic score helped define a novel type of insulin deficient non-autoimmune diabetes in sub-Saharan Africa." (PMID 42049600, 2026). "Type 1 diabetes (T1D) is a chronic autoimmune disease, increasingly common in the pediatric population, characterized by a progressive destruction of insulin-secreting β-cells of the pancreas." (PMID 40989118, 2025). "Encapsulation of insulin-producing cells holds significant therapeutic potential for treating type 1 diabetes (T1DM)." (PMID 40755902, 2025). "There seem to be two types of type 1 diabetes: autoimmune (where there is a severe deficit of insulin secretion due to the damage of insulin-producing beta cells in the pancreas) and idiopathic (where no autoimmune mechanisms are involved, and the cause is currently unknown)." (PMID 40141192, 2025). "In type 1 diabetes (T1D), insulin deprivation drives increased skeletal muscle catabolism, underscoring the importance of adequate protein to offset losses." (PMID 41305580, 2025). "In addition, reinforcement learning algorithms, such as Q-learning, have been utilized to provide personalized insulin doses for type 1 diabetic patients based on real-time CGM device measurements and patient-specific parameters, including exercise and alcohol intake." (PMID 41049970, 2025). "A limitation of our study may result from the different circumstances and family resources that the children encountered at home during the COVID-19 pandemic, which may play a role in the treatment of young children with type 1 diabetes and could affect the amount of insulin needed." (PMID 40406224, 2025).